PTCSC3 (papillary thyroid carcinoma susceptibility candidate 3)
Diseases named in the same sentence as PTCSC3 in open-access papers (continued):
Sharing a sentence is not in itself a finding about the gene and the disease.
gastric cancer (4 papers, 2021 to 2024). A primary or metastatic malignant neoplasm involving the stomach. "LncRNA including XLOC_009167, D16366, and PTCSC3 are potential biomarkers that predict lung cancer, hepatocellular cancer, and gastric cancer, accordingly." (PMID 36059090, 2022). "For example, lncRNA PTCSC3 can negatively regulate the proliferation, invasion and migration of gastric cancer cells." (PMID 34394184, 2021). "For example, lncRNA PTCSC3 could distinguish gastric cancer patients from healthy individuals and predict the poor overall survival of patients." (PMID 38610003, 2024).
thyroid tumor (4 papers, 2014 to 2022). A benign or malignant neoplasm affecting the thyroid gland. "Among 17 lincRNAs, the PTCSC3 has been reported as highly thyroid-specific, and found to be downregulated in thyroid tumor tissues and thyroid cell lines." (PMID 32324757, 2020). "Using quantitative PCR, PTCSC3 expression was revealed to be strongly downregulated in thyroid tumor tissues, and it was demonstrated that the restoration of PTCSC3 expression in PTC cells inhibited cell growth and affected the expression of numerous genes." (PMID 25289082, 2014).
periodontitis (3 papers, 2019 to 2024). An acute or chronic inflammatory process that affects the tissues that surround and support the teeth. "Periodontitis-affected PDLSC proliferation was suppressed by overexpression of PTCSC3, which also resulted in the downregulation of TLR4." (PMID 39063437, 2024). "Increased expression levels of PTCSC3 can improve periodontitis by inhibiting PDLSC levels and reducing TLR4 levels." (PMID 39063437, 2024). "PTCSC3 is a regulatory molecule that potentially modifies inflammatory responses in periodontitis by downregulating TLR4." (PMID 39063437, 2024). "Consistently, our study also showed that PTCSC3 overexpression is an inhibitor of the proliferation of periodontitis-affected PDLSCs." (PMID 31196168, 2019). "Due the fact that PTCSC3 was downregulated in periodontitis, to recover this downregulation, this study performed PTCSC3 overexpression." (PMID 31196168, 2019). "The key finding of the present study is that PTCSC3 was downregulated in periodontitis-affected PDLSCs and overexpression of PTCSC3 may improve periodontitis by inhibiting the proliferation of PDLSCs and downregulating the expression of TLR4." (PMID 31196168, 2019). "PTCSC3 overexpression also led to the inhibited proliferation of periodontitis-affected PDLSCs." (PMID 31196168, 2019). "Interestingly, our study proved that PTCSC3 was likely an upstream inhibitor of TLR4 in periodontitis-affected PDLSCs." (PMID 31196168, 2019). "In conclusion, PTCSC3 was downregulated in periodontitis, and overexpression of PTCSC3 may improve periodontitis by inhibiting the proliferation of PDLSCs and downregulating TLR4." (PMID 31196168, 2019). "Comparing to healthy PDLSCs, PTCSC3 was significantly downregulated, while TLR4 mRNA was significantly upregulated in periodontitis-affected PDLSCs (p < 0.05), indicating the involvement of PTCSC3 and TLR4 in the pathogenesis of periodontitis." (PMID 31196168, 2019). "Linear regression showed that expression levels of PTCSC3 and TLR4 were significantly and inversely correlated in periodontitis-affect PDLSCs." (PMID 31196168, 2019). "Our RNA-seq data showed that PTCSC3 was likely downregulated in periodontitis, and its expression levels were inversely correlated with toll-like receptor 4 (TLR4), which promotes periodontitis." (PMID 31196168, 2019). "Therefore, it will be reasonable to hypothesize that PTCSC3 may also participate in periodontitis." (PMID 31196168, 2019). "Expression of PTCSC3 and TLR4 mRNA in 34 cases of periodontitis-affected PDLSCs and 34 cases of healthy PDLSCs was detected by RT-qPCR." (PMID 31196168, 2019). "In vitro cell proliferation assay was performed to investigate the effects of PTCSC3 and TLR4 on proliferation of periodontitis-affected PDLSCs." (PMID 31196168, 2019). "This study aimed to investigate the role of PTCSC3 in periodontitis and explored its interactions with TLR4 by performing overexpression experiments, which recovered the downregulation of PTCSC3." (PMID 31196168, 2019). "In this study we found that PTCSC3 was downregulated, while toll-like receptor 4 (TLR4) was upregulated in periodontal ligament stem cells (PDLSCs) isolated from periodontitis affected teeth that in PDLSCs isolated from healthy teeth." (PMID 31196168, 2019). "Therefore, overexpression of PTCSC3 may serve as a potential therapeutic target for periodontitis." (PMID 31196168, 2019). "PTCSC3 and TLR4 were dysregulated in individuals affected by periodontitis." (PMID 39063437, 2024). "Dysregulation of PTCSC3 has been reported in non-cancerous disorders notably osteoporosis and periodontitis." (PMID 37644548, 2023). "Compared with control (C) and negative control (NC) groups, PTCSC3 overexpression led to significantly inhibited proliferation of 2 cases of periodontitis-affected PDLSCs (p < 0.05)." (PMID 31196168, 2019). "In addition, dysregulation of PTCSC3 has been reported in non-cancerous disorders notably osteoporosis and periodontitis." (PMID 37644548, 2023).
periodontitis (continued). "Therefore, lncRNA PTCSC3 may regulate the proliferation of PDLSCs and TLR4 expression to improve periodontitis." (PMID 31196168, 2019). "PTCSC3 was significantly downregulated, and TLR4 was significantly upregulated in PDLSCs from the teeth of individuals with periodontitis, respectively, but not from the teeth of healthy subjects." (PMID 39063437, 2024). "PTCSC3 overexpression led to the downregulation of TLR4 in PDLSCs isolated from periodontitis affected teeth, while TLR4 overexpression failed to significantly affect PTCSC3." (PMID 31196168, 2019). "Expression levels of PTCSC3 and TLR4 were only significantly and inversely correlated in PDLSCs isolated from periodontitis affected teeth but not in PDLSCs isolated from healthy teeth." (PMID 31196168, 2019). "It is worth noting that certain pathological mediators may exist between PTCSC3 and TLR4 due to the fact that expression levels of PTCSC3 and TLR4 were only significantly correlated in periodontitis-affected PDLSCs, but not in healthy PDLSCs." (PMID 31196168, 2019).
prostate carcinoma (3 papers, 2023 to 2024). A carcinoma that arises from epithelial cells of the prostate gland. "By considering the five-year survival rates and using both Kaplan-Meier curve and multivariable Cox analysis, we realized that PTCSC3 downregulation is linked to poorer long-term survival and prognosis for prostate cancer patients." (PMID 38997703, 2024). "PTCSC3 was found to be downregulated in prostate cancer, and its low levels were associated with short overall survival in patients." (PMID 38997703, 2024). "In conclusion, PTCSC3 acts as a sponge for miR-182-5p in prostate cancer regulating its expression and thereby influencing tumor progression." (PMID 38997703, 2024). "We chose CWR-R1 and DU-145 prostate cancer cells with lower PTCSC3 expression for in vitro cell assays." (PMID 38997703, 2024). "In our experiment, we quantified the PTCSC3 expression and found it to be lower in both prostate cancer serum and cell specimens compared to the control group." (PMID 38997703, 2024). "These reversion assays stated the regulatory role of the PTCSC3/miR-182-5p axis in prostate cancer cells." (PMID 38997703, 2024). "From the expression trend of PTCSC3, we explored its impact on the progression of prostate cancer and patient prognosis." (PMID 38997703, 2024). "This allowed us to uncover the molecular mechanism of PTCSC3 in controlling prostate cancer progression." (PMID 38997703, 2024). "Prognostic data from 125 prostate cancer patients revealed that those in the PTCSC3 low-group had shorter survival times than the PTCSC3 high-group (HR = 3.13, 95% CI = 1.36–7.25, Log-rank P value = 0.01)." (PMID 38997703, 2024). "This research underscores PTCSC3’s potential as a prognostic biomarker for prostate cancer, offering a new direction and theoretical foundation for patient treatment." (PMID 38997703, 2024). "The level of PTCSC3 in serum and cell samples of prostate cancer was quantitatively measured using RT-qPCR assays." (PMID 38997703, 2024). "This study aims to investigate the expression and molecular mechanism of lncRNA PTCSC3 (PTCSC3) in prostate cancer in order to develop new prognostic and therapeutic biomarkers." (PMID 38997703, 2024). "Transwell assay demonstrated that PTCSC3 overexpression inhibited prostate cancer cell behavior." (PMID 38997703, 2024). "As a potential prognostic biological factor for prostate cancer, PTCSC3 may regulate the progression of prostate cancer by sponging miR-182-5p and affect the prognosis of patients." (PMID 38997703, 2024). "We first assessed the levels of PTCSC3 in serum samples from 125 prostate cancer patients." (PMID 38997703, 2024). "In addition, the patients were divided into low-group (n = 64) and high-group (n = 61) based on the mean expression of PTCSC3 in prostate cancer." (PMID 38997703, 2024). "PTCSC3 may mediate the progression of prostate cancer by targeting and negatively regulating miR-182-5p." (PMID 38997703, 2024). "In this paper, we verified that the suppressor PTCSC3 is downregulated in prostate cancer." (PMID 38997703, 2024). "Taken together, this study elucidated that PTCSC3 was reduced in prostate cancer." (PMID 38997703, 2024). "Similarly, we observed downregulation of PTCSC3 in prostate cancer cells through RT-qPCR assays." (PMID 38997703, 2024). "However, the function of PTCSC3 in prostate cancer requires further exploration." (PMID 38997703, 2024). "It was hypothesized that high PTCSC3 levels may alleviate the progression of prostate cancer." (PMID 38997703, 2024). "This implies that PTCSC3 may serve as a potential biomarker for prostate cancer." (PMID 38997703, 2024). "Thus, PTCSC3 may be a potential prognostic biomarker for prostate cancer." (PMID 38997703, 2024). "Multivariable Cox analysis and related forest plots described that PTCSC3 (P = 0.01), TNM stage (P = 0.03), lymphatic metastasis (P = 0.03) and Gleason score (P = 0.04) are independent prognostic factors for prostate cancer." (PMID 38997703, 2024).
thyroid (3 papers, 2013 to 2022). "The first lncRNA studied in PTC, the so-called papillary thyroid carcinoma susceptibility candidate 3 (PTCSC3), was found to be downregulated in TC." (PMID 35804851, 2022). "In this manner, PTCSC3 loss could drive thyroid carcinogenesis by upregulating miR-574-5p." (PMID 35804851, 2022). "PTCSC3 expression is strictly thyroid-specific and is dramatically downregulated in thyroid tumor tissues and thyroid cell lines." (PMID 23599737, 2013).
breast carcinoma (2 papers, 2023 to 2024). "Elevated PTCSC3 levels are also suggested to negatively influence the activity or movement of breast cancer and laryngeal squamous cell cancer cells." (PMID 38997703, 2024).
osteoporosis (2 papers, 2023). A condition of reduced bone mass, with decreased cortical thickness and a decrease in the number and size of the trabeculae of cancellous bone (but normal chemical composition), resulting in increased fracture incidence. "Therefore, PTCSC3 can be proposed as a potential diagnostic biomarker for patients with osteoporosis." (PMID 37644548, 2023). "PTCSC3 is not only overexpressed in plasma samples of patients with osteoporosis, but it also has a positive correlation with osteoporosis stages." (PMID 37644548, 2023). "It has been reported that the LncRNA, PTCSC3, is upregulated in osteoporosis and the apoptosis of osteoblasts, and could, therefore, also be used as a potential therapeutic target for osteoporosis." (PMID 36879309, 2023).
cervical carcinoma (1 paper, 2021). A carcinoma arising from either the exocervical squamous epithelium or the endocervical glandular epithelium. "For example, lncRNA PTCSC3 inhibited cervical carcinoma cell proliferation and invasion by sponging miR-574-5p, and LINC00052 inhibited metastasis by regulating miRNA-574-5p in colorectal cancer." (PMID 34050132, 2021).
follicular adenoma (1 paper, 2020). "Similarly to PTCSC3, NRG1 was also earlier associated with follicular adenoma." (PMID 33551988, 2020).
laryngeal squamous cell carcinoma (1 paper, 2019). A squamous cell carcinoma that arises from the larynx. "We, in the present study, investigated the potential involvement of PTCSC3 in laryngeal squamous cell carcinoma (LSCC) and explored its interactions with STAT3." (PMID 31171714, 2019).
myocardial infarction (1 paper, 2019). Gross necrosis of the myocardium, as a result of interruption of the blood supply to the area, as in coronary thrombosis. "By comparing the co-expression with ceRNA networks, five lncRNAs (SNHG9, LINC02202, UBAC2-AS1, PTCSC3 and myocardial infarction associated transcript (MIAT)) and 32 genes (such as PIK3R1, PTPRB) were found to be shared." (PMID 31534842, 2019).
tumor (36 papers, 2013 to 2026). "Previous study indicated that long non‐coding RNA papillary thyroid carcinoma susceptibility candidate 3 (PTCSC3) is an anti‐tumour LncRNA,27 but the explicit mechanism still remains to be identified." (PMID 34337858, 2021). "PTCSC3 can influence the expression of genes associated with DNA replication, recombination and repair, tumor cell viability and motility and tumor morphology." (PMID 29416703, 2018). "Further study revealed that SNP rs944289 abolishes the binding site of both C/EBPα and C/EBPβ, which bind and activate the PTCSC3 promoter, thus, SNP rs944289 predisposes to PTC through downregulating tumor suppressive lncRNA PTCSC3." (PMID 23725405, 2013). "The tumour‐suppressive function of PTCSC3 and the underlying mechanisms were clarified." (PMID 34337858, 2021). "LncRNA PTCSC3 was significantly suppressed in PTC tumor tissue and it could affect PTC predisposition and carcinogenesis through downregulating the MMP-9 and VEGF expression via the S100A4 pathway." (PMID 32284745, 2020). "Papillary thyroid cancer susceptibility candidate 2 (PTCSC2) and 3 (PTCSC3) are two novel thyroid-specific lncRNAs that may serve as tumor suppressors." (PMID 27802187, 2017). "PTCSC3 is a tumor suppressor lncRNA, identified in thyroid after careful investigation of the surrounding locus in linkage with rs944289, a tag SNP on chromosome 14q13.3." (PMID 41489907, 2026). "LncRNAs like PTCSC3 mainly exert their function as a tumor suppressor, and its downregulation can place individuals at a higher risk for developing malignancy and/or concerning genomic instability." (PMID 41154428, 2025). "LncRNA PTCSC3, a tumor suppressor, suppresses EMT and invasion via the Wnt/β-catenin signaling pathway, and the downregulation of PTCSC3 is associated with a higher risk of cancer and aggressiveness." (PMID 41154428, 2025). "While some lncRNAs, such as PTCSC3, act to suppress tumors, their downregulation correlates to an increase in angiogenesis and aggressiveness of the tumor." (PMID 41154428, 2025). "PTCSC3 functions as a tumor suppressor lncRNA to regulate essential cellular processes such as apoptosis, cell proliferation, migration, invasion, angiogenesis, and epithelial-to-mesenchymal transition." (PMID 37644548, 2023). "The tumor-suppressive function of PTCSC3 has been documented in several cancers including thyroid, gastric, laryngeal, breast, cervical, oral, lung, and glioma cancers." (PMID 37644548, 2023). "In gastric tumors, PTCSC3 was significantly correlated with stages of tumors, differentiation, tumor diameter, and metastasis." (PMID 37644548, 2023). "It has been reported that the expression level of PTCSC3 is decreased in the tissue samples and cell lines of CC patients, indicating that it plays a tumor-suppressive role in CC." (PMID 37644548, 2023). "The increased expression of PTCSC3 causes repression of LSCC cell proliferation; thus, the lncRNA acts as a tumor suppressor." (PMID 36359888, 2022). "PTCSC3 is the tumor suppressor lncRNA of TC and negatively regulates STAT3/INO80 to attenuate the resistance to doxorubicin that favors prognosis." (PMID 35915656, 2022). "Overexpression of PTCSC3 significantly inhibited the aerobic glycolysis and tumour growth of PTC cells." (PMID 34337858, 2021). "The tumours derived from PTCSC3 overexpressed cell line were significant smaller when compared with the control group." (PMID 34337858, 2021). "LncRNA PTCSC3 has been characterized as a tumor suppressor, while its roles in other human diseases are unclear." (PMID 31196168, 2019). "Restoration of PTCSC3 expression in thyroid cell lines inhibits cell growth, suggesting that this protein has a tumor suppressor function." (PMID 31247975, 2019). "The expression levels of PTCSC2 and PTCSC3 are strongly down-regulated in PTC tumor tissues and in TC tissues, respectively, compared with neighboring normal tissues." (PMID 27802187, 2017).